CCL5 (C-C motif chemokine ligand 5)
Diseases named in the same sentence as CCL5 in open-access papers (continued):
Sharing a sentence is not in itself a finding about the gene and the disease.
cancer (continued). "Simultaneously increasing CCL5 expression on cancer cells increased the anti-cancer effect even more." (PMID 39114657, 2024). "And it has been demonstrated that the low expression of gene CCL5 decreases the number of CD8+ T cells in cancer cells." (PMID 39693287, 2024). "On the other hand, cancer cell-secreted CCL5 induces the polarization of monocytes into M2 macrophages and recruits CCR5+ TAMs." (PMID 39114657, 2024). "For example, it was seen here that high-dose radiation increased measured levels of CCL5 released by the cancer cells (0, 10, and 18 Gy regimens resulted in culture levels of 1912, 2430, and 2412 pg CCL5/ml, respectively)." (PMID 39231199, 2024). "Previous research has shown that macrophage‐secreted C‐C motif chemokine ligand 5 (CCL5) stabilizes PD‐L1 in vitro and in vivo, promotes immune escape, potentially offering therapeutic and prognostic significance for human cancers." (PMID 39344205, 2024). "The study here saw that high-dose radiation increased the secretion levels of CCL5 by the cancer cells, while conventional doses of radiation suppressed CCL5 secretion." (PMID 39231199, 2024). "AT releases higher levels of adipose-derived cytokines, such as leptin, Interleukin-6 (IL-6), and CC-chemokine ligand 5 (CCL5), promoting cancer proliferation and invasion." (PMID 38800384, 2024). "The chemokine receptor CCL5 was described as overexpressed in tumors, contributing to microenvironment remodeling, cancer progression, DNA repair, and related processes." (PMID 38674102, 2024). "The CCL5-induced attraction of monocytes to metastatic cancer cells indicates that CCL5 is indirectly critical to the organization of metastasis rather than directly acting on cancer cells." (PMID 36831623, 2023). "CCL5, known for its involvement in cancer cell migration and metastasis, was also identified among the hub genes." (PMID 37816585, 2023). "The CCL5/CCR5 axis contributes to cancer cell proliferation, metastasis, and the formation of an immunosuppressive microenvironment via the PI3K/Akt or STAT3 signaling pathway." (PMID 37553567, 2023). "In fact, CCL5 promotes Treg infiltration, and cancer-FoxP3 (C-FoxP3) expressed on these T-regs promotes PD-L1 expression, which rationalizes targeting CCL5 in combination with PD-L1 inhibitors." (PMID 37488598, 2023). "For example, the MHC class and CD274 work in cancer and immune cells, and CCL5, CXCL10 and IFNB1 are downstream of ISRE and induce immune cell infiltration into cancer tissue." (PMID 37543704, 2023). "Taken together, the results indicate the crucial role of CCL5 and CXCL10 in mediating T cell recruitment in RB1-deficient cancer cells." (PMID 37937640, 2023). "As reported for gastric cancer, TAMs are capable of promoting cancer progression by activating CCL5/CCR5/STAT3 signaling." (PMID 36173487, 2023). "In prostate cancer, it is shown that CCL5-derived from MSCs and cancer cells, through suppressing the nuclear translocation of androgen receptors, increases the metastatic potential of cancer cells due to inhibiting androgen receptor signaling." (PMID 38022534, 2023). "A previous study also established a relationship between TGF-β and CCL5 and proved that TGF1β uses CCL5 to enhance glycolysis in cancer cells." (PMID 36761981, 2023). "By producing chemokines, CA-MSCs increase the development and cell proliferation in cancer cells; for example, increasing the expression of CCL5 chemokine by BM-MSCs increases proliferation, migration, metastasis, and malignant behaviors in cancer cells." (PMID 38022534, 2023). "This chemokine, also called CCL5, is produced by platelets, and has been shown to play an important role in cancer progression, namely in invasion, metastasis, angiogenesis, and immune cell infiltration." (PMID 38532749, 2023).
cancer (continued). "One study reported that coculture of BM-MSCs with PCa cells upregulated their expression of CCL5, which was shown to block AR nuclear translocation and a resultant increase in cancer stem cells and PCa cell invasiveness." (PMID 37025604, 2023). "The CCL4 and CCL5 chemokines play a vital role in various cancer types in terms of metastasis, invasion, and poor clinical disease outcomes." (PMID 38067251, 2023). "Preclinical studies in various cancer models have demonstrated CCL5 as a double-edged sword in cancer." (PMID 37040518, 2023). "Experiments in vivo and in vitro have shown that acquired resistance to trastuzumab in cancer patients was inhibited by maraviroc blocking CCL5/CCR5 binding." (PMID 37141250, 2023). "Our results highlight the effects of DHEA as a potential anti-cancer agent in TNBC by targeting the chemokine CCL5." (PMID 36765778, 2023). "During the course of cancer therapy, a high change rate of IL‐6, IL‐8, CXCL10, CCR1, and CCL5 was significantly associated with poor PFS." (PMID 37062076, 2023). "CCL-5 produced by cancer cells induces cancer cell proliferation but also evokes infiltration of T cells and dendritic cells (DCs) into the TME." (PMID 37736898, 2023). "What is more, CCL2 and C-C Motif Chemokine Ligand 5 (CCL5) can promote cancer cell proliferation, survival, motility, epithelial–mesenchymal transition (EMT), and stemness." (PMID 37895310, 2023). "Following cancer cell death, several cytokines (i.e., IL-1, IL-6, IL-8, IL-12, IL-18) and chemokines such as CCL5 are released that lead to the mobilization and activation of additional immune cells, further contributing to the host’s defense against cancer." (PMID 37371127, 2023). "In this review, RKIP’s regulatory role on the expression of CCL5 in cancer cells influences the recruitment of macrophages to the TME." (PMID 36765912, 2023). "Fibrocytes secrete only IL23 and IFNγ, which were suppressed upon co-culture, whereas cancer cells or fibrocytes secrete CCL5, IL-1ra, CD54, CXCL10, MIF, CXCL1, IL-6, and IL-8, which was not affected by co-culture." (PMID 36241617, 2022). "Previous studies have found that when cancer cells reduce CCL5 production, CXCL9 expression also decreased." (PMID 35145917, 2022). "Adipocytes enhanced MDA-MB-231 cancer cell invasiveness, through CCL5 signaling, which negatively correlated with OS." (PMID 36077676, 2022). "In summary, cancer cells activate macrophages, which, in turn, activate the CCL5/CCR5 axis in cancer cells." (PMID 35054987, 2022). "Cox regression analysis was used to understand the prognostic value of CCL5 mRNA expression in 33 different TCGA cancer types." (PMID 35982911, 2022). "The enhanced levels of CCL5 lead to high GLUT1 expression on the surface of cancer cells and provide enough energy for the proliferation of breast tumor cells as well as angiogenesis." (PMID 36430633, 2022). "MDSCs drive cancer escape by inhibiting the activity of T cell adaptive immunity, while CCL5 is crucial for the generation and growth of MDSCs." (PMID 35327361, 2022). "The CAFs secrete cytokines, including CCL5 and matrix metalloproteinases (MMPs), to further promote cancer metastasis." (PMID 35280699, 2022). "Another well studied chemokine in cancer is CCL5, which greatly promotes carcinogenesis, stroma formation, cancer progression and metastasis." (PMID 36325334, 2022). "Didymin was able to deplete its secretion, thus hampering the metastatic and proliferative activities of cancer cells and proving its role in cancer prevention via targeting CCL5 pathway, and possibly protect against phthalate-induced infertility." (PMID 35163492, 2022). "MDA-MB-231 cells co-cultured with bone marrow MSCs enhanced de novo secretion of CCL5 (RANTES), which then induced cancer cell motility, invasion, and metastasis." (PMID 35455040, 2022).
cancer (continued). "In order to precisely describe what chemokine is involved in T-cell homing, a transcriptomic approach, conducted in seven types of human cancers, proposed that CCL5 and CXCL9 expression is correlated with CD8A expression in the tumors." (PMID 36429101, 2022). "CCL5 plays a role in multiple cancer stages, including cancer cell proliferation, migration, invasion, angiogenesis and immune regulation." (PMID 36387070, 2022). "Through these cancer cell stimulations, CCL5 derived from mesenchymal stem cells further boosts cancer cells’ motility, invasion, and metastasis." (PMID 36497322, 2022). "As an important member of the CC subfamily of chemokines, CCL5 was upregulated in various types of cancer." (PMID 37181790, 2022). "Together, our results show that the Macrophages-aPKCɩ-CCL5 feedback loop between mesenchymal-like cancer cells and TAMs promotes CCA progression and chemoresistance." (PMID 35033156, 2022). "Some of the significant cancer hallmark terms are epithelial-mesenchymal transition (MSX1, CXCL12, SCG2, SLIT2), KRAS signaling up (F13A1, ADAMDEC1), inflammatory response (CCL5, VIP), IL-6/JAK/STAT3 signaling (CXCL13)." (PMID 35486660, 2022). "This team has demonstrated that macrophages differentiated in the presence of pancreatic tumor cells (PANC1 and PT45) and treated with Poly (I:C) secrete more CXCL10 and CCL5 which trigger the cytotoxic activity of TC-Mφ against cancer cells." (PMID 33402730, 2022). "qPCR was performed for the treated murine 4T1, LLC, and CT26 cancer cell lines, and the data showed that the total expression levels of CCL5, CXCL9, and CXCL10 were significantly increased after tucidinostat treatment." (PMID 36352411, 2022). "It has been suggested that CCL5 can be used as a biomarker and predictor for the development of anti-cancer treatment strategies." (PMID 36387070, 2022). "It has been established that blocking either CCL5 or CCR5 immediately after diagnosis would stall cancer cell invasion." (PMID 36430633, 2022). "Cancer-associated adipocytes (CAA) are characterized by a smaller size, they secrete more chemokine ligand 2 and 5 (CCL2, CCL5), IL-1β, IL-6, leptin, VEGF and TNF-α, but lower the expression of adiponectin." (PMID 35741450, 2022). "CCL5 has been correlated with malignancy, cancer cell proliferation and progressive disease in a number of types of pathologies, such as gynecological, genito-urinary and digestive cancers." (PMID 36429101, 2022). "We observed that immunostimulatory chemokines such as CXCL9, CXCL10, CXCL11, CCL4, and CCL5 were consistently down‐regulated for the tumors with high Hh activity across the 14 cancer types." (PMID 34841742, 2022). "CCL5 and CXCL12 have been linked to cancer progression, epithelial–mesenchymal transition, immune evasion, metastasis, and worse prognosis." (PMID 36613922, 2022). "To this aim, we measured CCL2, CCL3, CCL4, and CCL5 by CBA in TCM from different cancer types or in cultures of BM cells stimulated with the same TCMs or with recombinant cytokines involved in MDSC differentiation." (PMID 35064009, 2022). "CCL5 is considered to contribute to the biological function of a variety of cancer types, but its specific mechanism is still unclear." (PMID 36033472, 2022). "The results showed that higher CCL5 expression significantly predicts poor survival and enhanced cancer progression (OS: P<0.001, HR=1.919; PFS: P<0.001, HR=1.927)." (PMID 35982911, 2022). "In silico, in vitro and in vivo studies blocking the CCL5/CCR5 axis show cancer cells become less invasive and less malignant, and the extracellular matrices produced are less oncogenic." (PMID 36430633, 2022). "The effect of CCL5 was diminished after inhibiting CD4+ T cells, suggesting that Th cells mediate CCL5-induced cancer-promoting phenotypes of TAMs." (PMID 35740686, 2022). "Previous data suggested that high intratumoral expression of CD8+ T cell-attracting chemokine CCL5 is correlated with better prognosis in several types of cancers." (PMID 36352411, 2022).
cancer (continued). "In this model, TAMs derived from PyMT mice bearing homozygous null CCL5 (CCL5−/−) exhibited a cancer-suppressing phenotype compared to TAMs in control (CCL5+/+) PyMT mice." (PMID 35740686, 2022). "There is evidence that CCR5, one of interface genes in IBT_Her2+_TNBC, interacts with CCl5 to promote tumorigenesis at the beginning of cancer." (PMID 35992864, 2022). "While HLA-I+ cancer cells released key effector cytokines and chemokines, such as CXCL10, CCL4, CCL5, and IFN-γ, HLA-I–deficient cancer cells had a limited release of proinflammatory cytokines." (PMID 35503263, 2022). "Notably, our data showed that CRC cells secreted TSG-6 could trigger a paracrine activation of JAK2-STAT3 signaling and reprogram normal fibroblasts into cancer-associated fibroblasts, which exhibited upregulation of pro-metastatic cytokines (CCL5 and MMP3) and higher movement ability." (PMID 35280699, 2022). "For instance, downregulation of circABCB10 via the miR-326/CCL5 axis promoted cancer cell ferroptosis and inhibited the progression of rectal cancer." (PMID 35342359, 2022). "In carcinomas, some authors have described the relationship between high levels of CCL5 or CCR5 expression in tumors and advanced stages, including a proangiogenic role and the stimulation of cancer stem cells." (PMID 36613922, 2022). "In one study, weakly metastatic cancer cells stimulated co-cultured MSCs, a source of CAFs, into secreting the chemokine CCL5, thereby promoting the invasion of the cancer cells and metastasis." (PMID 34646829, 2021). "CCL5 expression levels were significantly associated with inferred CD8+ T cell, dendritic cell, and NK cell abundance across multiple cancer types." (PMID 34030676, 2021). "Other top differentiated genes that resulted from the presence of platelets included cancer-associated inflammatory cytokines CXCL5 and CCL5 which are associated with invasiveness, metastasis and platelet guided formation of a metastatic niche." (PMID 34189439, 2021). "In macrophage cultures, PIC led to a significant CCL5 increase, which is NF-κB-dependent and interferon-I-dependent, while in cancer specimens, a moderate expression was detected." (PMID 33809574, 2021). "The expression levels of six chemokine genes (CCL5, CXCL9, CXCL13, CXCL10, CXCL11, and CCL19) were significantly associated with the image-based immune scores across all 13 tested cancer types." (PMID 34030676, 2021). "The involvement of the CCR5 ligand, CCL5, in cancer and specifically in HCC has been extensively studied." (PMID 34638423, 2021). "For example, a recent report suggested NK cells recruit dendritic cells (DC) into murine solid tumours via CCL5, XCL1 and XCL2, and both chemokine expression and the presence of DC were associated with improved survival in selected cancer types." (PMID 34452316, 2021). "CCL5, CXCL9, CXCL13, CXCL10, and CXCL11 were also among the top chemokine genes associated with the gene expression-based immune scores across multiple cancer types." (PMID 34030676, 2021). "CAF produce numerous factors acting on cancer cells to promote glycolytic metabolism, proliferation, invasion, angiogenesis and metastatic colonisation, including CCL5, CXCL10, IL‐6, TGFα, SDF and versican." (PMID 34841720, 2021). "In the experimental settings, human adipose stem cells (ASC) stimulated breast cancer motility and invasion through production of CCL5, as a response to cancer cells." (PMID 34063254, 2021). "Cancer-linked bone obliteration in NSCLC, the upstream receptor of CCL-5, Runt-related Transcription Factor-3 (RUNX3), was rather helpful when expressed a little." (PMID 34336101, 2021). "Previously, we reported that RKIP inhibits F4/80+ macrophage infiltration by decreasing CCL5 expression in cancer cells." (PMID 34465801, 2021). "In particular, therapeutic blockade of CCL5-CXCR2 interaction by disrupting production of CCL5 or CXCR2 antagonist has demonstrated promising antitumor efficacies in several preclinical cancer models." (PMID 35003065, 2021).
cancer (continued). "CCL5 immunoreactivity was markedly detected in stromal cells adjacent to carcinoma cells, as compared to those in normal mammary stroma." (PMID 33671956, 2021). "In cancer cells, the interaction between CCL5 and CCR5 increased the expression of glucose transporters, glucose uptake, glycolysis and subsequent ATP production." (PMID 32098198, 2020). "The inflammatory chemokine (CCL5) contributing to metastasis of cancer cells was downregulated in A549 and A129L transfected with EZH2‐shRNA2# in both mRNA and protein levels." (PMID 31855281, 2020). "Similar to other chemokines, CCL5 causes migration, invasion, and epithelial-to-mesenchymal transition (EMT) of cancer cells via its receptor, which is related to the activation of hedgehog, Wnt/β-catenin, and the Akt/PKB→nuclear factor κB (NF-κB) pathways." (PMID 33076281, 2020). "Since the CCR5/CCL5 interaction is involved in the motility, migration, and invasion of various cancer cells, we analyzed the functional significance of this interaction in the migration of HCC cells." (PMID 32260550, 2020). "CCL5 knockdown by small interfering RNA (siRNA) reduces cancer cell growth, migration and invasiveness and induces apoptosis." (PMID 32630699, 2020). "Since CCL5 induces the proliferation of cancer cells that express CCR5, we evaluated the role of CCL5 in inducing CCR5 in HCC cells." (PMID 32260550, 2020). "Previous studies have shown that host CCL5 can work as both pro- and anticancer molecule, generating a controversy in its role in cancer immunity." (PMID 32218434, 2020). "CCL5 participates in angiogenesis, which is associated with an increase in vascular endothelial growth factor (VEGF) expression in cancer cells and vascular endothelial cells via the activation of CCR1 and CCR5." (PMID 33076281, 2020). "Cancer cells express receptors for CCL5 and increased levels of CCL5 are present in cancerous tissue." (PMID 32098198, 2020). "Residual Her2-driven breast tumors, responsible for cancer recurrence, are characterized by a pro-inflammatory gene expression program, including CCL5." (PMID 32630699, 2020). "Cancer, a condition in which cells grow abnormally, presents with the increased expression of CCL5 and CCR5." (PMID 32098198, 2020). "The silencing of interferon regulatory factor 4 (IRF4), a transcription factor overexpressed by cHL cells and involved in cancer cell proliferation and survival, decreases CCL5 secretion." (PMID 32630699, 2020). "The CCL5/CCR5 axis has been demonstrated to promote cancer cell migration through the recruitment and modulation of inflammatory cell activities, followed by the generation of an immunosuppressive environment including TAMs and MDSCs in BC." (PMID 31991604, 2020). "The Oncomine database was used to perform a meta-analysis, and the difference between cancer tissue and normal tissue of CCL5 expression was the most significant." (PMID 32081834, 2020). "Metabolic analysis revealed that cancer cells treated with CCL5 reflected increased anabolic pathways, which are responsible for synthesizing complex molecules." (PMID 32098198, 2020). "Cancer cells, when treated with CCL5, showed increased expression of glucose transporters which increased glucose uptake and therefore glycolysis." (PMID 32098198, 2020). "CCL5 stabilizes PD-L1 expression in cancer cells due to the up-regulation of COP9 signalosome 5 (CSN5), a modulator of PD-L1 deubiquitination which has been associated with significantly shorter survival." (PMID 32630699, 2020). "In certain cancer cells CCL5 has been found to promote angiogenesis, through down-regulation of miR-200b via the PI3K/Akt pathway." (PMID 32784743, 2020). "This present study found that CCL5 mRNA was significantly overexpressed in KIRC tissues compared with normal tissues adjacent to cancer." (PMID 33173412, 2020). "Tregs recruitment by cancer-Foxp3 was impaired by the neutralization of CCL5, inhibiting the growth of PDAC." (PMID 32680511, 2020).